MRPL52 (mitochondrial ribosomal protein L52)
Synonyms: mL52
Tractability: Small molecule: a structure with a bound ligand is known. PROTAC: its protein half-life has been measured.
Gene: Protein-coding gene on chromosome 14 (22,829,875 to 22,835,037, forward strand). Ensembl gene ENSG00000172590.
Subcellular location: Mitochondrion
Subcellular location (Human Protein Atlas): Mitochondria; Nucleoplasm
Pathways (Reactome):
Metabolism of proteins: Mitochondrial ribosome-associated quality control; Mitochondrial translation elongation; Mitochondrial translation initiation; Mitochondrial translation termination
Gene Ontology:
Molecular function: protein binding; structural constituent of ribosome
Biological process: mitochondrial translation; translation
Cellular component: mitochondrial large ribosomal subunit; mitochondrion; mitochondrial inner membrane
Genetic constraint (gnomAD): Loss-of-function variants: 19 observed, 23.6 expected, observed/expected ratio (o/e) 0.8, 90% interval 0.56 to 1.18. The upper end of that interval is the gene's LOEUF score, 1.18, which puts it in group 5 of 6, group 1 being the genes least tolerant of losing a copy. Missense variants: 143 observed, 150.55 expected, observed/expected ratio (o/e) 0.95, 90% interval 0.83 to 1.09. Synonymous variants: 47 observed, 58.36 expected, observed/expected ratio (o/e) 0.81, 90% interval 0.64 to 1.03.
Homologues: Orthologues: macaque MRPL52 (92% identical), dog MRPL52 (87% identical), rabbit MRPL52 (86% identical), pig MRPL52 (84% identical), guinea pig MRPL52 (83% identical), mouse Mrpl52 (83% identical), rat Mrpl52 (80% identical), chimpanzee MRPL52 (62% identical), tropical clawed frog mrpl52 (49% identical), zebrafish mrpl52 (48% identical), Drosophila melanogaster mRpL52 (33% identical).
Diseases named in the same sentence as MRPL52 in open-access papers:
MRPL52 is named in the same sentence as 9 diseases in open-access papers, as found by Europe PMC text mining. Sharing a sentence is not in itself a finding about the gene and the disease. The quoted sentences say what the papers report.
breast carcinoma (5 papers, 2024 to 2025). "MRPL52 regulates hypoxia-induced apoptotic resistance and metastatic initiation of breast cancer cells by facilitating PINK1/Parkin-dependent mitophagy and transactivating the reactive oxygen species (ROS)-Notch1-Snail pathway, respectively." (PMID 39859078, 2025). "The expression of MRPL52 is upregulated in breast cancer, particularly in hypoxic breast cancer cells, which regulates the ROS/Notch1/Snail signaling pathway to promote EMT, migration, and invasion, which enhances apoptotic resistance and metastatic potential." (PMID 40371222, 2025). "The expression of mitochondrial ribosomal protein L52 (MRPL52) is elevated in human breast cancer and significantly correlated with invasive clinical pathological features and higher metastatic risk." (PMID 39179991, 2024). "Breast cancer patients with high MRPL52 expression have a poor prognosis." (PMID 39859078, 2025). "Mechanistically, MRPL52 helps breast cancer cells resist hypoxia-induced apoptosis." (PMID 41407038, 2025). "MRPL52 is upregulated in breast cancer, particularly in metastatic cases." (PMID 39859078, 2025). "Notably, MRPL52, a component of the large subunit of the mitoribosome, is a transcriptional target of HIF1α and is overexpressed in breast cancer relative to adjacent normal tissue." (PMID 41407038, 2025).
colon cancer (2 papers, 2021 to 2025). "We noted an opposite effect of this gene in our current study, namely that silencing MRPL52 could inhibit proliferation of different mutational colon cancer cells." (PMID 33806918, 2021). "Gene dependency analysis shows that silencing the expression of MRPL52 effectively inhibits the proliferation of colon cancer cells." (PMID 40371222, 2025). "This suggests that hnRNPK may play a significant role in tumorigenesis by regulating the splicing of MRPL33 pre-mRNA.Through proteomics analysis and public transcriptomics data, MRPL52 has been identified as a key protein in colon cancer cells." (PMID 40371222, 2025). "Finally, the GTPase ERAL1, mitochondrial ribosomal proteins ERAL1, MRPL11, MRPL15, MRPL30, MRPL37, MRPL40, and MRPL52 were determined to be hub proteins with a commonly down-regulated trend in four berberine-treated colon cancer cell lines." (PMID 33806918, 2021).
colorectal cancer (2 papers, 2016 to 2021). A primary or metastatic malignant neoplasm that affects the colon or rectum. "Interestingly, recent research demonstrated that high expression of MRPL52 might predict good survival in colorectal cancer." (PMID 33806918, 2021).
lymph node metastasis (1 paper, 2021). "MRPL52 overexpression was strongly correlated with more advanced clinicopathological features, including histological grade, lymph node metastasis and tumor size." (PMID 34158854, 2021).
oral squamous cell carcinoma (1 paper, 2025). "A prior investigation demonstrated that LINC00152 contributes to the proliferation and expansion of tumors in oral squamous cell carcinoma by increasing the transcriptional activity of mitochondrial ribosomal protein L52 (MRPL52), which is mediated by upstream transcription factor 1 (TF1)." (PMID 41299664, 2025).
ovarian carcinoma (1 paper, 2025). A malignant neoplasm originating from the surface ovarian epithelium. "MRPL51 and MRPL52 are upregulated in ovarian cancer patients, with the low expression of both MRPL51 and MRPL52 associated with a worse prognosis." (PMID 39859078, 2025).
cancer (4 papers, 2016 to 2025). A tumor composed of atypical neoplastic, often pleomorphic cells that invade other tissues. "In our study, MRPL52 was identified as a cancer-promoting oncogene which mediated the apoptotic resistance and metastatic initiation of hypoxic BC cells." (PMID 34158854, 2021). "We found that MRPL52 might mediate the influence of a heterogeneous tumor microenvironment on cancer cell behaviours and could be a promising therapeutic target for effective treatment of metastatic BC." (PMID 34158854, 2021). "Therefore, MRPL52 can be considered as a molecular mechanism that mediates the hypoxia-induced malignant phenotype of tumor as well as the adaptation of cancer cell to hypoxia." (PMID 34158854, 2021). "In cancer cells, hypoxia-induced HIF-1 upregulates the mitochondrial ribosomal protein (MRPL52), promoting PINK1/Parkin-dependent mitochondrial autophagy to clear ROS and protect cancer cells." (PMID 40723842, 2025). "Less information are available for six of the genes in the panel in relation to cancer namely the ITPRIP, FRMD6, CPXCR1, SLC38A9, MRPL52 and GFRA4." (PMID 27609023, 2016).
tumor (3 papers, 2020 to 2024). "We investigated whether the high expression of MRPL52 in BC is partially caused by the hypoxic tumor environment." (PMID 34158854, 2021). "Since EMT is a master mechanism that initiates the process of tumor migration and invasion, we further observed the role of MRPL52 in EMT." (PMID 34158854, 2021). "Interestingly, expression levels of HERC3, KCNN2, and MRPL52 were not significantly varied in tumor group and control group." (PMID 38918720, 2024).
MRPL52 also shares sentences with these, for which no sentence is quoted: lung adenocarcinoma (1 paper).